MIR30D (microRNA 30d)
Synonyms: hsa-mir-30d; MIRN30D; mir-30d
Gene: MicroRNA gene on chromosome 8 (134,804,876 to 134,804,945, reverse strand). Ensembl gene ENSG00000199153.
Gene Ontology:
Biological process: miRNA-mediated post-transcriptional gene silencing
Cellular component: RISC complex
Homologues: Orthologues: chimpanzee ptr-mir-30d (100% identical), macaque mml-mir-30d (100% identical), pig ssc-mir-30d (97% identical), guinea pig MIR30D (93% identical), mouse Mir30d (93% identical), dog MIR30D (80% identical), tropical clawed frog xtr-mir-30a (76% identical). Paralogues in human: MIR30A (73% identical), MIR30E (73% identical), MIR30B (50% identical), MIR30C2 (50% identical), MIR30C1 (46% identical).
Diseases named in the same sentence as MIR30D in open-access papers:
MIR30D is named in the same sentence as 5 diseases in open-access papers, as found by Europe PMC text mining. Sharing a sentence is not in itself a finding about the gene and the disease. The quoted sentences say what the papers report.
lung adenocarcinoma (1 paper, 2025). A carcinoma that arises from the lung and is characterized by the presence of malignant glandular epithelial cells. "Many of the identified CNAs also included well-known cancer-related miRNA genes, including MIR92B (ch1q21), MIR30B (ch8q24), and MIR30D (ch8q24), whose frequent amplifications in lung adenocarcinoma have been reported previously, and many others that have not been reported previously." (PMID 40867048, 2025).
tumor (3 papers, 2017 to 2022). "KEGG enrichment showed that in PNT1A cells, Menin significantly (p = 4.8E–08) regulates 12 microRNAs (MIR1-2; MIR133a-1; MIR155; MIR15a; MIR16-1; MIR29a; MIR29b-1; MIR30a; MIR30d; let-7a-1; let-7d; let-7f-1), widely shown to function as tumor suppressors in PC." (PMID 34711954, 2022). "This discrepancy might be due to the limited region of MIR30D gene on chromosome 8q24 which is less influenced by repeated replication during tumor progression." (PMID 28356144, 2017).
MIR30D also shares sentences with these, for which no sentence is quoted: cancer (3 papers); cervical squamous cell carcinoma (1); thyroid cancer (1).